KPLCE (KPRP N-terminal and LCE C-terminal like protein)
Synonyms: C1orf68; LEP7; XP32
Tractability: Antibody: the Human Protein Atlas places it where antibodies can reach.
Gene: Protein-coding gene on chromosome 1 (152,719,522 to 152,720,470, forward strand). Ensembl gene ENSG00000198854.
Subcellular location (Human Protein Atlas): Plasma membrane; Cytosol
Gene Ontology:
Biological process: epidermis development
Genetic constraint (gnomAD): Loss-of-function variants: 6 observed, 6.43 expected, observed/expected ratio (o/e) 0.93, 90% interval 0.51 to 1.72. That is too few expected variants to judge how well the gene tolerates losing a copy. Missense variants: 320 observed, 322.13 expected, observed/expected ratio (o/e) 0.99, 90% interval 0.91 to 1.09. Synonymous variants: 128 observed, 122.17 expected, observed/expected ratio (o/e) 1.05, 90% interval 0.91 to 1.21.
Homologues: Orthologues: chimpanzee KPLCE (98% identical), pig KPLCE (79% identical), rabbit KPLCE (78% identical), rat Kplce (78% identical), guinea pig KPLCE (76% identical), mouse Kplce (76% identical), dog KPLCE (75% identical). Paralogues in human: LCE1F (20% identical), LCE2D (20% identical), LCE1E (19% identical), LCE2C (19% identical), LCE2B (18% identical), LCE5A (18% identical), LCE1D (18% identical), LCE2A (18% identical), LCE3A (17% identical), LCE3B (17% identical), LCE3D (17% identical), LCE3E (17% identical), and 8 more.
Diseases named in the same sentence as KPLCE in open-access papers:
KPLCE is named in the same sentence as 6 diseases in open-access papers, as found by Europe PMC text mining. Sharing a sentence is not in itself a finding about the gene and the disease.
KPLCE shares sentences with these, for which no sentence is quoted: Candidemia (1 paper); infectious disease (1); periodontal disease (1); periodontitis (1); psoriasis (1); tuberculosis (1).